ERG (ETS transcription factor ERG)
Diseases named in the same sentence as ERG in open-access papers (continued):
Sharing a sentence is not in itself a finding about the gene and the disease.
prostate carcinoma (continued). "These include NanoString detection of two well-established biomarkers for prostate cancer PCA3 and TMPRSS2:ERG." (PMID 35454901, 2022). "The presence of ERG gene fusion; from developing prostatic intraepithelial neoplasia (PIN) lesions to hormone resistant high grade prostate cancer (PCa) dictates disease progression, altered androgen metabolism, proliferation and metastasis." (PMID 35508713, 2022). "ERG and TMPRSS2 fusion is found in about 50% of prostate cancers, and ETV1 and TMPRSS2 fusion is found in 5% of prostate cancers." (PMID 36289913, 2022). "Together, these data show that SWI/SNF ATPase inactivation specifically leads to genome-wide collapse of the AR, FOXA1, ERG and MYC-activated core enhancer circuitry in prostate cancer cells." (PMID 34937944, 2022). "De novo motif and binding analysis for the regulation of transcription (BART) analyses of AU-15330-compacted sites identified DNA-binding elements for major oncogenic transcription factors in prostate cancer, including AR, FOXA1, HOXB13 and ERG." (PMID 34937944, 2022). "In the future, we will further explore the difference between the TMPRSS2: ERG fusion gene and the TMPRSS2 gene through basic and clinical research, as well as the prognostic role in prostate cancer." (PMID 34951103, 2022). "Bioinformatic analysis has uncovered various fusions in the 5’ untranslated region of TMPRSS2 (21q22) when it is fused to ERG (21q22), ETV1 (7p21), ETV4 (17q21), or ETV5 (3q27), resulting in the overexpression of ETS and ETS-related genes in prostate cancer." (PMID 35563163, 2022). "TMPRSS2-ERG rearrangement, the most common ETS gene fusion in prostate cancer, brings ERG expression under androgen control via androgen receptor-mediated TMPRSS2 regulation and results in over-expression of ERG protein." (PMID 35513774, 2022). "FZD8 is directly targeted and activated by ERG, which is involved in bone metastasis of prostate cancer by regulating Wnt-11 and TGF-β signaling to stimulate epithelial–mesenchymal transition in prostate cancer." (PMID 36579559, 2022). "Cell migration in a trans-well assay was compared between RWPE-ERG, RWPE-empty vector, RWPE-KRAS and the ERG-negative prostate cancer cell line PC3." (PMID 33554122, 2021). "The most common genetic alteration in prostate cancer consists of a chromosomal rearrangement between the androgen-regulated gene TMPRSS2 and the ETS transcription factor ERG." (PMID 34638309, 2021). "Tian and colleagues used a newly established prostate cancer cell line (PC3c), derived from PC-3, to assess the role of the TMPRSS2:ERG fusion transcript in the formation of bone metastases." (PMID 33634124, 2021). "An example is TMPRSS2–ERG, generated in prostate cancer via an intron deletion between TMPRSS2 and ERG on chromosome 21q22.2-3." (PMID 33557176, 2021). "The expression of common prostate cancer biomarkers, including AR, AMACR, PSA, PSMA, ERG, and neuroendocrine markers (synaptophysin, chromogranin A and CD56) were continually assessed across PDX generations." (PMID 34413304, 2021). "The origins of the most common fusion in prostate cancer, TMPRSS2/ERG is accredited to intronic AR binding in combination with DNA damage or inflammatory signaling." (PMID 34409300, 2021). "The correlation between ERG and SOX9 protein levels was verified in clinical samples of prostate cancer by IHC and in androgen-treated VCaP cells." (PMID 33634124, 2021). "It has been previously reported that ERG can drive TLR4 expression in prostate cells and that TLR4 signaling can contribute to an invasive phenotype in prostate cancer cells." (PMID 33554122, 2021). "Due to its high frequency in prostate cancer cases, the TMPRSS2:ERG fusion is considered to be relevant for the disease." (PMID 33634124, 2021).
prostate carcinoma (continued). "In prostate cancer, the ETS family members ERG as well as ETV1 are commonly rearranged and ectopic ERG expression by TMPRSS2-ERG fusion blocks NE differentiation." (PMID 34121659, 2021). "Nearly half of patients with prostate cancer have a translocation between the TMPRSS2 locus and ERG or another ETS family transcription factor, which places the transcription factor under the control of androgens." (PMID 34685470, 2021). "Akin to LEF1 degrader, ERG O'PROTAC induces the degradation of ERG and inhibits prostate cancer cell growth." (PMID 34397171, 2021). "In its original version, the PCPT RC includes age, race, PSA levels, family history of prostate cancer, results of a DRE, results of a prior biopsy, and when available, free PSA, prostate cancer antigen 3, and T2:ERG." (PMID 34477564, 2021). "While the role of SPOP protein differs depending on the tumor type, in prostate cancer, SPOP seems to function as a tumor suppressor and its targets for degradation, among others, include AR, ERG, steroid receptor coactivator 3 (SRC3), BRD4, MYC, and TRIM24." (PMID 33572160, 2021). "MiPS is a urine test for detecting two prostate cancer biomarkers: a piece of RNA made from the prostate cancer antigen 3 (PCA3), and another RNA marker that is found only when TMPRSS2 and ERG abnormally fuse (T2:ERG)." (PMID 34884946, 2021). "Another prostate cancer cohort study stratified the patients according to the exclusive expression pattern of TFF3 and ERG." (PMID 33916984, 2021). "TMPRSS2-ERG is a highly prevalent fusion gene in prostate cancer (∼50% of the diagnosed patients), resulting in TMPRSS2-driven up-regulation of ERG." (PMID 34891161, 2021). "We describe the case of a patient who developed lung and prostate cancers, both harboring the TMPRSS2:ERG fusion." (PMID 33419298, 2020). "The role of ERG and ETV1 in prostate cancer has been thoroughly studied, whereas the mechanisms whereby overexpression of ETV4 mediates oncogenesis in the prostate have not been investigated in depth." (PMID 32791988, 2020). "One of the most frequent promoter substitution (PS) events in cancer involve transcriptional activation of ERG through fusion with TMPRSS2, which occurs in approximately 40% of prostate cancers as a result of a genomic deletion on chromosome 17q2217." (PMID 33097743, 2020). "Purified His-ERG was bound to cobalt beads and used as bait to pull-down native EWS from prostate cancer cell line PC3 nuclear extract." (PMID 32915889, 2020). "Third, the ERG and PTEN-featured prostate cancer cases were derived from males who received RP or TURP, but when the inverse probability weighting method was used to balance the potential bias, the results were similar with the unweighted analysis." (PMID 32467600, 2020). "miR-1271 was shown to specifically target ETS-related gene (ERG) to further downregulate the expression of ERG and inhibit cellular processes in prostate cancer, which was in line with our results." (PMID 32448371, 2020). "Mechanistically, basic fibroblast growth factor (FGF2) secreted by endothelial cells leads to the upregulation of ETS related gene (ERG) expression and activation of the Akt/mTOR signaling pathway in prostate cancer cells to promote docetaxel resistance." (PMID 33425737, 2020). "Recently, we demonstrate that the transcription factor ERG, expressed by the TMPRSS2:ERG fusion gene, can directly transactivate the ESRRA gene in advanced prostate cancer." (PMID 32226548, 2020). "Combined analysis of the PCAWG and GTEx datasets leads to the hypothesis that a subset of prostate cancers, through genome rearrangement, hijack the promoters of androgen-responsive genes to increase ERG expression, resulting in an androgen-dependent overexpression of ERG." (PMID 32636365, 2020). "On a genetic level, about 50% of prostate cancer is characterized by gene fusion of the androgen responsive TMPRSS2 serin protease and the ETS-family transcription factor ERG." (PMID 33195694, 2020).
prostate carcinoma (continued). "It is important to note that early-onset patients are characterized by higher expression of AR and about 90% of these patients had ERG fusions and deletions of AR corepressor NCOR, which is significantly higher than the estimated 50% for all prostate cancers." (PMID 31366128, 2019). "In SCLC1, we detected a candidate fusion of the N terminus of the arginyltransferase ATE1 to the pointed (PNT), DNA binding and transactivation domains of ERG, an ETS-family transcription factor subject to frequent GOF fusion events in prostate cancer." (PMID 30348992, 2019). "In a high proportion of prostate cancers chromosomal rearrangements activate members of the ETS family of transcription factors, such as ERG." (PMID 31366128, 2019). "In PC TRIM25 is the E3 ubiquitin ligase of Ets related gene (ERG), an important transcription factor central for prostate cancers progression." (PMID 31137886, 2019). "More than half of all prostate cancers, particularly those of young patients, harbor fusions connecting the androgen-regulated TMPRSS2 gene with the transcription factor ERG." (PMID 31557128, 2019). "In total, 76 out of the 89 ERG fusions were TMPRSS2–ERG and affected 36% of all prostate cancer samples in the cohort." (PMID 31645765, 2019). "In prostate cancer, the ERG gene is frequently translocated to the TMPRSS2 promoter region, with the resulting TMPRSS2-ERG fusion protein expressed in ~50% of human prostate cancers." (PMID 30733438, 2019). "In addition to confirming known gene defects, we also identified several novel prostate cancer associated genes which may play important roles in the tumorigenesis of ERG-negative cancer type." (PMID 30150711, 2018). "In the patho-physiological context of prostate cancer, TMPRSS2-ERG fusion protein is presumably functioning in the presence of the wild type, untranslocated ERG protein." (PMID 29455671, 2018). "Four out of seven molecular subtypes of primary prostate cancer defined in the large Cancer Genome Atlas study of 333 tumors harbor fusion or overexpression of one of the ETS family genes, namely ERG, ETV1, ETV4 or FLI1." (PMID 29734647, 2018). "Article sets for ‘TMPRSS2:ERG or ETS-related gene’ and ‘prostate cancer’ were generated and compared (1 March 2017) using 867 and 138 391 articles, respectively." (PMID 29342271, 2018). "SPINK1 is overexpressed in approximately 10% of prostate cancers, and SPINK1 overexpression and ERG rearrangement appear to be mutually exclusive." (PMID 29581876, 2018). "In this study, we identified a pathway related to metastasis, involving ERG, CITED2, NCL, and AKT pathway, in prostate cancer." (PMID 30291252, 2018). "- TMPRSS2-ERG gene fusion leads to ETS-related gene (ERG) and steroidogenic enzyme AKR1C3 co-overexpression which promotes AR signaling and represents a promising target in prostate cancer." (PMID 30319966, 2018). "In prostate cancer, three members of the ETS family (ERG, ETV1, and ETV4) are commonly overexpressed due to chromosomal translocations." (PMID 30603056, 2018). "About 50% of prostate cancers carry a gene fusion involving the androgen-regulated serine protease TMPRSS2 and the ETS-transcription factor ERG." (PMID 28146062, 2017). "Members of the ETS transcription factor family are often implicated as oncogenic cancer drivers, and this is best exemplified by the role of ERG, and PEA3 subfamily members in prostate cancers [reviewed in 14]." (PMID 28859074, 2017). "In summary, these results demonstrate proof-of-principal that small molecule targeting of the ERG-ETS domain can suppress transcriptional activity and reverse transformed characteristics of prostate cancers aberrantly expressing ERG." (PMID 28465491, 2017). "Among the most common somatic genomic alterations in prostate cancer are rearrangements involving ETS-family transcription factors, of which ERG is the most common, seen in nearly half of all prostate tumors." (PMID 28186998, 2017).
prostate carcinoma (continued). "Interestingly, ERG rearrangement prevalence varies significantly by racial ancestry, suggesting that germline genetics and/or environmental factors could affect the frequency of somatic genomic alterations in prostate cancer." (PMID 28186998, 2017). "In prostate cancer patients, the presence of two well-known biomarkers in exosomes recovered from urine samples, such as the PCA-3 and TMPRSS2:ERG mRNAs, indicated an alternative strategy for early screening of the disease." (PMID 28098821, 2017). "To illustrate how INTEGRATE-Vis works we focused on a prostate cancer patient harboring the most prevalent gene fusion, TMPRSS2-ERG, that results in the marked increase in the expression of the oncogenic transcription factor ERG." (PMID 29259323, 2017). "In terms of TMPRSS2:ERG, we previously developed a PI polyamide targeting a common sequence in AR-related DNA break points among TMPRSS2 and ERG gene loci to repress TMPRSS2:ERG expression and prostate cancer cell growth." (PMID 28264478, 2017). "On the other hand, chromosomal rearrangements between TMPRSS2 and ERG (TMPRSS2:ERG), made by AR binding to the “breakpoint ARE” in this region, occur in around 50% of prostate cancers." (PMID 28264478, 2017). "Several studies have demonstrated the anti-tumor efficacy of YK-4-279 in Ewing’s sarcoma, ERG- and ETV1-mediated prostate cancer and EWS-FLI1-induced leukemia." (PMID 29212266, 2017). "Prostein and PSA correctly detected 82% of cases, HOXB13 and PSA labeled 94.2% of cases correctly, AR and PSA detected 100% of cases, and ERG and PSA recognized 88% of prostate cancer metastases." (PMID 28555048, 2017). "For example, we found that the prognostic value of SOX9 and mTOR expression was limited to ERG-positive cancers while the prognostic value of NBS1, SENP145 CD14746 only seen in ERG-negative prostate cancers." (PMID 28515422, 2017). "Our data revealed that MAP3K7 deletion is often heterogeneous in prostate cancer and prevents TMPRSS2:ERG fusion, while TMPRSS2:ERG fusion allows MAP3K7 deletion." (PMID 26684029, 2016). "Fusion between TMPRSS2 and ERG, placing ERG under the control of the TMPRSS2 promoter, is the most frequent genetic alteration in prostate cancer, present in 40–50% of cases." (PMID 27536883, 2016). "It has been shown that ERG increases expression of neurotransmitter reporters and TMPRSS2-ERG fusion blocks neuroendocrine cell differentiation to allow prostate cancer proliferation." (PMID 27626693, 2016). "Here, we constructed a heterogeneity tissue microarray (TMA) comprising samples from 10 different tumor areas of 189 prostate cancers each in order to study the sequence of two frequent molecular alterations, i.e. 6q15 deletion and TMPRSS2:ERG fusion." (PMID 26684029, 2016). "The considerable fraction of 44.7 % heterogeneously ERG positive cancer foci and the continuous increase of ERG positive areas with tumor focus size found in our study further suggests that ERG fusion may not always be an initiating event but can also occur later during prostate cancer evolution." (PMID 27530104, 2016). "Because basal epithelial cells are lost during prostate cancer development, it is possible that TMPRSS2/ERG-dependent prostate tumors retain more basal cells, resulting in high levels of miR-205 in the tumors." (PMID 27191272, 2016). "The data show substantial heterogeneity for MAP3K7 deletion in prostate cancer and suggest that MAP3K7 deletion largely prevents development of TMPRSS2:ERG fusions." (PMID 26684029, 2016). "Among the commonly used prostate cancer cell lines, VCaP is the only cell line that harbors TMPRSS2/ERG translocation and expresses ERG protein." (PMID 27191272, 2016). "The use of EVs was also examined as a potential platform to non-invasively differentiate Bx Pos versus Bx Neg patients via the detection of known prostate cancer genes TMPRSS2:ERG, BIRC5, ERG, PCA3 and TMPRSS2." (PMID 27144529, 2016).
prostate carcinoma (continued). "Tumor SC_9009 expressed a fusion transcript involving the 5′ exons of TMPRSS2 and 3′ exons of ERG, consistent with the commonly observed TMPRSS2-ETS family rearrangements that occur in 40– 60% of prostate cancers." (PMID 27167109, 2016). "Given the expression of the ets genes ERG and ETV1 in prostate cancers, YK-4-279 was also tested in prostate cancer cell lines, demonstrating its ability to reduce cell motility and tumor invasion." (PMID 26885691, 2016). "In the pathophysiological context of prostate cancer, TMPRSS2-ERG fusion proteins are presumably functioning in the presence of the wild type, untranslocated ERG protein." (PMID 27285981, 2016). "Therefore, we cannot determine whether miR-205 is regulated by ERG in prostate cancer cells." (PMID 27191272, 2016). "We aimed to evaluate ERG and SOX9 as potential biomarkers of docetaxel response in metastatic castration-resistant prostate cancer (mCRPC) patients." (PMID 27863438, 2016). "Further classification of this cohort into prostate cancer subtypes, revealed that 90 % of the JAK1 deep deletions occurred in the ‘ERG fusion’ subtype (p = 4.542e−3)." (PMID 27366948, 2016). "Previously, we found that ERG undergoes ubiquitination and then is deubiquitinated by USP9X in prostate cancer cells to prevent its proteasomal degradation." (PMID 27626314, 2016). "About 50% of prostate cancers are characterized by the TMPRSS2:ERG fusion, which results in overexpression of the ERG transcription factor and massive transcriptional changes." (PMID 26030748, 2015). "A strong overlap of the identified eight FAIRE-seq peaks was found with known players in prostate cancer including AR, FOXA1, ERG, bromodomains BRD2 and BRD3 and, interestingly, MYC." (PMID 26412853, 2015). "We recently have shown that GRPR is an ERG and ETV1 target gene in prostate cancer, using a genome-wide scale and exon-level expression microarray platform." (PMID 26097883, 2015). "The two ETS factors ERG and ETV1 reprogram the androgen receptor cistrome with consequences for androgen ablation therapy in prostate cancer." (PMID 26462019, 2015). "Recent studies have suggested that ILK is a therapeutically targetable mediator of ERG-induced EMT and transformation in prostate cancer." (PMID 25852822, 2015). "Expression of GRPR, both at mRNA and protein levels, was detected in ERG and ETV1 rearrangement-positive prostate cancer cell lines VCaP and LNCaP, respectively." (PMID 26097883, 2015). "The study introduces to the prostate cancer research community 259 men who have been profiled with copy number, transcript expression, TMPRSS2:ERG gene fusion status and tissue microarray data." (PMID 26501111, 2015). "More than half of all prostate cancers, particularly those of young patients, carry gene fusions linking the androgen-regulated TMPRSS2 gene with the transcription factor ERG." (PMID 26230842, 2015). "ERG and SPINK1 positive tumors have been proposed to describe discrete molecular subtypes of prostate cancer." (PMID 26172920, 2015). "We recently have shown that gastrin-releasing peptide receptor (GRPR) is an ERG and ETV1 target gene in prostate cancer, using a genome-wide scale and exonlevel expression microarray platform." (PMID 26316886, 2015). "YK-4-279 inhibited ERG and ETV1 derived malignant phenotypes in prostate cancer cells both in vitro and in vivo." (PMID 26462019, 2015). "Our group has shown that YK-4-279 binds to ERG and ETV1 and inhibits their activity in prostate cancer cell lines and show anti-metastatic activity in vivo." (PMID 26462019, 2015). "Given our findings indicating that ERG-positive prostate tumor cells exhibited expression of neurotransmitter receptors and that nicotine enhanced tumor cell growth in vitro, we hypothesized that growth of ERG-positive prostate cancer would be enhanced in patients that smoked." (PMID 26310325, 2015).